TNF (tumor necrosis factor)
Diseases named in the same sentence as TNF in open-access papers (continued):
Sharing a sentence is not in itself a finding about the gene and the disease.
pulmonary fibrosis (continued). "Fuling, Yiyiren, and Dongguazi have been shown to treat bleomycin-induced pulmonary fibrosis by reducing serum levels of TGF-β1 and TNF-α." (PMID 38074219, 2023). "The inflammatory activities of IL-1β, IL-6, MPO, TGF-β1, and TNF-α in the lung tissues of both normal control rats and BLM-induced lung fibrosis rat models were determined." (PMID 35268069, 2022). "It has been reported that chitosan administration ameliorates pulmonary fibrosis in rats through inhibition of the proinflammatory cytokines including TGF-β1, and TNF-α." (PMID 35836166, 2022). "Pretreatment with CDMP protected mice pulmonary fibrosis via significantly downregulating the secretion of TGF-β1 along with the decrease of IL-1β, IL-6, and TNF-α levels." (PMID 36339607, 2022). "• The overexpression of cytokines (i.e., TNF-α, IL-2, IL-10, IL-1, and IL-6) leads to development lung damage, cell death, severe pneumonia, ARDS, lung fibrosis, local or systemic thrombosis and multiple organ failure." (PMID 35422702, 2022). "Activation of inflammatory molecules particularly TNFα and TGFβ promotes inflammation; damaging ECM protein components and triggering myofibroblast differentiation that leads to the development of lung fibrosis." (PMID 35083615, 2022). "One of the main factors involved in SSc is TNF-α, and serum levels of TNF-α are elevated in patients with SSc and favor the development of pulmonary fibrosis and pulmonary arterial hypertension." (PMID 36614095, 2022). "An increase in total cell numbers and enrichment of inflammatory cytokines (TNF-α and IL-1β) in BALF are the hallmarks of BLM—induced pulmonary fibrosis." (PMID 35628193, 2022). "The transcription of many inflammatory cytokines, such as TNFα, IL6, IL1β and TGFβ, are vital in development of lung fibrosis." (PMID 35083615, 2022). "In experimental pulmonary fibrosis, MMP-9 promotes the release of transforming growth factor-β (TGF-β) and TNF-α, which has been enhanced in rabbits with acute gouty arthritis." (PMID 36297105, 2022). "A comparison of blood cytokines between HPS-1 patients with pulmonary fibrosis (PF) and patients with familial pulmonary fibrosis revealed a distinct inflammatory signature in HPS-1 with elevation of IFN-γ, TNF and IL-814." (PMID 36302964, 2022). "It’s worth to note that Pathways in fibrosis consisted of TNF signaling pathway (bta04668), Jak-STAT signaling pathway (bta04630) and other signaling pathway involved in lung fibrosis on KEGG website." (PMID 34580234, 2021). "The aqueous extract of H. cordata has effects of anti-pulmonary fibrosis by inhibiting the expression of superoxide dismutase, malondialdehyde, hydroxyproline, interferon-γ (IFN-γ), and TNF-α." (PMID 34658873, 2021). "According to the existing studies, the development of pulmonary fibrosis in the patients with SARS-CoV-2 infection is accompanied by the increased expression of cytokines such as TGF-β, TNF-α, IL-1β, IL-6 and IL-13." (PMID 34876129, 2021). "TNFα can also be inhibited pharmacologically with the drug pirfenidone (PFD) that can block TNFα translation in RAW264.7 cells and is used to treat idiopathic pulmonary fibrosis." (PMID 32039742, 2020). "In our investigation, when compared with the control group, the levels of MDA, TNF-α, and IL-6 were dramatically increased and SOD was dramatically reduced in Blm-treated pulmonary fibrosis mice lung tissues." (PMID 33192501, 2020). "Increased levels of TNF-α have been found in the lungs of IPF patients and in animal models for pulmonary fibrosis." (PMID 32747751, 2020). "The secretion of cytokines, including IL-1β, IL-6, TNF-α, and MCP-1, plays a certain role in the pathogenesis of pulmonary fibrosis." (PMID 31947943, 2020). "Cytokines such as TNF-α, ILs, and transforming growth factor-β (TGF-β) are of great importance in the local pulmonary injury and inflammatory response of pulmonary fibrosis." (PMID 33817248, 2020).
pulmonary fibrosis (continued). "DHP mainly regulated pulmonary fibrosis-related inflammatory genes and signaling pathways, such as IL1β, IL4, IL5, IL6, TGFβ1, and TNFα." (PMID 31105564, 2019). "Many researchers investigated the effect of TNF-α in IPF, and found that TNF-α plays an important role in the development of interstitial inflammation and pulmonary fibrosis." (PMID 29997685, 2018). "Taken together, in the present study, SML decreased the tissue expression of TNF-α and TGF-β1, and improved pulmonary fibrosis in rats, which was much effective at medium and high doses compared with DEX." (PMID 29997685, 2018). "These cells secrete pro-inflammatory and pro-fibrotic cytokines and chemokines, including IL-1β, IL-6, TNF-α, and MCP-1, which influence the pathogenesis of pulmonary fibrosis." (PMID 30250465, 2018). "In accordance with the present findings, UCMSC administration decreased inflammation and inhibited the expression of IL-1, IL-6, TNF, collagen I, and TGF-β in bleomycin-induced lung fibrosis in mice." (PMID 29954457, 2018). "As a mechanism for suppression of pulmonary fibrosis in Mdk KO mice, the suppressed expression of TNF‐α and TGF‐β in the lung tissue of Mdk KO mice was possibly involved in the pathogenesis of pulmonary fibrosis." (PMID 28811360, 2017). "Noting that, TNF-α and TGF-β kept a persistent higher level at the end of 16th, which promotes the development of lung fibrosis." (PMID 28977826, 2017). "According to their findings, TNF-α controlled fibrogenesis by regulating TGF-β expression, and asbestos-induced ROS triggered lung fibrosis by activating latent TGF-β." (PMID 26685284, 2016). "At the model of partially reversible pulmonary fibrosis by ELISA we evaluated levels of cytokines (TGF-β, IL-1β and TNF-α) in the lung parenchyma and serum on the 3rd after BLM treatment." (PMID 25927611, 2015). "It is well known that increased expression levels of the proinflammatory cytokines IL-6, IL-1β and TNF-α and decreased expression levels of the anti-fibrotic cytokine IFN-γ are involved in the pathogenesis and progression of pulmonary fibrosis." (PMID 25092105, 2014). "Basic pharmacological studies confirmed that dexamethasone can regulate gene transcription and expression of a variety of inflammatory cytokines, such as IL-6, TNF-α, and TGF-β, which is closely related to radiation-induced lung fibrosis." (PMID 24744681, 2014). "Our previous study further indicated that thalidomide was able to downregulate the levels of TNF-α and TGF-β in the lungs of rats, and exhibit an attenuating effect on pulmonary fibrosis." (PMID 24520265, 2014). "In the present study, the main objective was to investigate the effects of CAPE on some key mediators including TGF-β1, TNF-α and prostaglandin E2 (PGE2) involved in profibrotic/antifibrotic balance and pathogenesis of idiopathic pulmonary fibrosis (IPF)." (PMID 23997916, 2013). "Inflammatory cytokines, including tumor necrosis factor (TNF) and interleukin (IL), are also important in the development of pulmonary fibrosis." (PMID 21423633, 2011). "Iloprost prevents bleomycin-induced pulmonary fibrosis, possibly by upregulating antifibrotic mediators (IFNγ and CXCL10) and downregulating pro-inflammatory and pro-fibrotic cytokines (TNFα, IL-6, and TGFβ1)." (PMID 20302663, 2010). "Mice exposed to silica and treated with an anti-TNF-α antibody show significantly reduced lung collagen deposition; conversely administration of recombinant TNF-α increases lung fibrosis." (PMID 19298665, 2009). "In the rat study investigating the effects of Ole on pulmonary fibrosis induced by intratracheal bleomycin, TNF-α, IL-13, TGFβ1, Platelet-derived growth factor (PDFG), lung collagen index and MDA increased significantly in BALF, but Ole prevented pulmonary fibrosis by reversing these effects." (PMID 40233022, 2025).
pulmonary fibrosis (continued). "Studies have shown that 4 weeks of moderate-intensity aerobic exercise suppresses the expression of TGF-β1 and inflammatory pathways TLR4/TNF-α and SRB/NLPR3, which, in turn, suppresses the expression of macrophage-derived IL-17A, thereby ameliorating silica-induced pulmonary fibrosis." (PMID 39796197, 2025). "A growing number of studies have shown that Th1 cells exert resistance to lung fibrosis by inducing an inflammatory response in the lung through the release of pro-inflammatory cytokines IL-2, interferon-gamma (IFN-γ), tumor necrosis factor(TNF), IL-12, and IL-18 production." (PMID 40433386, 2025). "However, after treatment with LP03, the concentrations of TNF-α, IL-6, and IL-1β were notably reduced, highlighting the protective effect of LP03 against the inflammatory response in BLM-induced pulmonary fibrosis." (PMID 40994978, 2025). "Proinflammatory cytokines TNFα and pro-fibrotic genes in lung tissue were downregulated by 50 mg/kg BGT-004, the reducing effect was similar to the PFD (pirfenidone, 300 mg/kg, b.i.d), a drug used to treat lung fibrosis." (PMID 37016043, 2023). "Translational studies have demonstrated that despite a pathogenic role of TNF-α in favouring chronic lymphocytic alveolitis and fibroblast activation, and vice versa, a lack of TNF-α seems to prevent bleomycin-induced lung fibrosis." (PMID 37175894, 2023). "In a BLM-induced pulmonary fibrosis model, MSC treatment was reported to decrease the expression levels of IL-10, interferon (IFN)-γ, and tumor necrosis factor (TNF)-α as well as the concentration of transforming growth factor (TGF)-β1 in the lungs, resulting in decreased collagen expression." (PMID 36870972, 2023). "Iguratimod can inhibit the expression of TNF-α, IL-1, IL-6 and MMP-9 to reduce bleomycin-induced alveolar inflammation and pulmonary fibrosis in mice, suggesting that iguratimod may become an effective strategy for the treatment of pulmonary fibrosis." (PMID 37809072, 2023). "TNF-α, TGF-β1, IL-6, MCP-1, and MMP-7 are inflammatory mediators and profibrotic factors involved in lung tissue damage and play a significant role in the initiation and progression of pulmonary fibrosis." (PMID 37047142, 2023). "In the same way, CD300c2 enhances high-mobility group box protein-1 (HMGB-1)-induced macrophage activation to produce tumor necrosis factor (TNF), which is a leukocyte chemoattractants, resulting in the accumulation of augmented immune cells, inflammation, and the aggravation of lung fibrosis." (PMID 37569370, 2023). "JTE-013 was found to regulate the physiological processes of pulmonary fibrosis and reduce BLM-induced inflammatory pulmonary fibrosis, as evidenced by the results of H&E and Masson staining, and, the expression changes of IL-4, IL-5, IFN-γ, and TNF-α in BALF." (PMID 37895915, 2023). "ADAM17 is involved in a variety of inflammatory processes, including activation and release of TNF, modulation of neuregulins such as AREG, and being a necessary cofactor for IL6 trans-signaling, which has been shown to promote pulmonary fibrosis in bleomycin injury." (PMID 36291184, 2022). "The lung fibrosis of TNF-Tg mice in the MTX administration group was not reversed, but more severe tissue fibrosis appeared around the bronchus and alveoli." (PMID 35600883, 2022). "Therefore, suppressing TNF-α, TGF- β, CTGF and ET-1 expressions involves the degradation of collagen and mitigating of lung fibrosis, which partially describes the anti-fibrotic mechanism of PL in IPF." (PMID 36271442, 2022). "As we expected, IL-6, TNF-α, CRP, and D-dimer levels were all reduced after lenalidomide treatment, which is consistent with previous findings that lenalidomide attenuated IL-6 and TNF-α secretion in a pulmonary fibrosis model and mantle cell lymphoma." (PMID 35967862, 2022).
pulmonary fibrosis (continued). "MSCs are found to increase the angiogenesis process and alveolar reepithelization, reducing markers like TNF alpha, TGF beta, and COL I and III, reducing the growth of myofibroblasts and increasing survivability of endothelium leading to attenuated pulmonary fibrosis and even reversing them." (PMID 35782071, 2022). "In this experiment, we found that Yifei decoction combined with MitoQ could significantly reduce the expression of IL-6, IL-1β, TNF-α, and MDA and increase the activity of GSH-Px and SOD in lung tissue of rats with pulmonary fibrosis induced by bleomycin." (PMID 34135982, 2021). "This impaired wound healing can generate a disequilibrium in favor of the pro-fibrotic factors such as tumor necrosis factor alpha (TNF-), platelet-derived growth factor (PDGF) or transforming growth factor beta (TGF-), which will mediate the development and further progression of lung fibrosis." (PMID 34026781, 2021). "All these indicate that TGF-β, TNF-α, IL-1β, IL-6, IL-13, ACE2 and autophagy inhibition may be the key factors in pulmonary fibrosis induced by SARS-CoV-2." (PMID 34876129, 2021). "For instance, the transgenic TNF-α mice that overexpress murine TNF-α under the control of the human surfactant protein C promoter are more tolerant to bleomycin or active TGF-β1 induced pulmonary fibrosis." (PMID 35082682, 2021). "This study also supports the previous finding that high levels of NFkB, TNF, SFTPC, MUC5B, and other proteins could promote lung fibrosis." (PMID 33362771, 2020). "STAT1 antisense oligonucleotides (ASON) could inhibit the secretion of TNF-α and ICAM-1 in alveolar macrophages (AMs), and STAT1 could become a target of treating pulmonary fibrosis." (PMID 33072088, 2020). "Additionally, TGF-β1 also modulates several signaling pathways, including activation of Smad, TNF-α and IL-1β, inhibition of AMPK activity, which induces EC injury and extracellular matrix production, thus promoting the progression of pulmonary fibrosis." (PMID 31611754, 2019). "According to our findings resulting from factor analysis and multi-regression assays, Npnt seemed to be correlated with the late phase of lung fibrosis as well as bronchial alterations, but was not related to initial inflammatory responses affected by TNF-α." (PMID 31130697, 2019). "The expression of miR-155 in human lung fibroblasts was upregulated by TNF-α and IL-1β and downregulated by TGF-β1; miR-155, which might target keratinocyte growth factor, promoted migration of fibroblasts and enhanced pulmonary fibrosis." (PMID 31013581, 2019). "In our study, we found that BALF TNF-α and IL-6 levels and lung TNF-α and IL-6 mRNA were markedly increased in the WT BLM group mice, indicating that 5-HT might promote the production of cytokines in pulmonary fibrosis." (PMID 29849496, 2018). "Also, TNF-α up-regulates the expression of TGF-β1, activates NF-κB, and promotes the proliferation, differentiation of fibroblasts finally induces pulmonary fibrosis." (PMID 29997685, 2018). "In conclusion, pirfenidone, prednisone and acetylcysteine can inhibit airsacculitis and pulmonary fibrosis in rat IPF models, and its mechanisms may be related with enhanced caveolin-1, reduced TNF-α, TGF-β1, PDGF." (PMID 27937011, 2017). "Discussion and conclusion: Pirfenidone, prednisone and acetylcysteine can inhibit airsacculitis and pulmonary fibrosis in rat IPF models, which may be related with enhanced caveolin-1, reduced TNF-α, TGF-β1, PDGF." (PMID 27937011, 2017). "However, after boosting with PA, high levels of proinflammatory cytokines such as TNF-α and IFN-γ were observed along with the lung fibrosis." (PMID 27203210, 2016). "Depletion of neutrophils might attenuate lung fibrosis and inflammation through down-regulating TGF-β1, TNF-α, IL-17, MMP-8 and TIMP-2." (PMID 27690127, 2016).
pulmonary fibrosis (continued). "Moreover, the reduced lung fibrosis observed with A-MWCNTs corresponded to decreased BALF levels of OPN and TNF-α, both which play important roles in inflammation and fibrosis." (PMID 27278808, 2016). "Additionally, TNF-α levels were elevated after repeated PA challenge, and increased levels of TGF-β1 were observed during the lung fibrosis stage." (PMID 27203210, 2016). "Previous studies indicate that TNF-α blockade inhibits bleomycin-induced pulmonary fibrosis in an animal model and that TNF-α receptor knockout mice are protected from asbestos-induced pulmonary fibrosis." (PMID 26114656, 2015). "Furthermore, it has been demonstrated that thalidomide inhibits the production of inflammatory cytokines, including TNF-α, TGF-β1 and nuclear factor-κB (NF-κB), thereby reducing the degree of pulmonary fibrosis." (PMID 24520265, 2014). "The data showed that TNF-α and IL-1β dramatically up-regulated not only in the acute phase of LPS-induced model but also 8 weeks later in the BLM-induced pulmonary fibrosis." (PMID 25465226, 2014). "To determine whether NNAV rendered the protection by inhibiting inflammatory process, we analyzed the serum inflammatory cytokines IL-1β and TNF-α in LPS-induced (acute phase) and BLM-induced pulmonary fibrosis." (PMID 25465226, 2014). "Similarly, BLM-sensitive IL-1 and TNF-α are produced in increasing amounts, and IL-1 receptor antagonists, anti-TNF antibodies and soluble TNF receptors alleviate the bleomycin-induced pulmonary fibrosis." (PMID 23558450, 2013). "To decipher the role of TNF and TNF-mediated inflammation in the development of fibrosis, we have utilized the bleomycin-induced animal model of Pulmonary Fibrosis and a series of genetically modified mice lacking components of TNF signaling." (PMID 17205112, 2006). "While IL-1β, TNF-α and IL-4, known for their implication in the extension of lung fibrosis, had no or limited effect on Cat K expression, both concentrations of TGF-β1 (1 and 10 ng/ml) reduced Cat K expression." (PMID 16045809, 2005). "This suggests that PFD may mitigate silicosis progression through modulation of TLR2-mediated NF-κB p50/p65 pathway activation, consequently reducing TNF and MMP9 production-two critical mediators of inflammatory response and extracellular matrix remodeling in pulmonary fibrosis." (PMID 40470053, 2025). "Within the BALF, levels of tumor necrosis factor-α (TNFα), osteopontin (OPN), monocyte chemoattractant protein-1 (MCP-1), and surfactant protein-D (SP-D) were significantly elevated in both wild-type (WT) and TG mice with lung fibrosis, compared to their respective saline-treated controls." (PMID 39329706, 2024). "In addition, TNF released by M1 macrophages changes the phenotype of macrophages and fibroblasts, delays tissue repair, and also produces TGF-β1 and platelet-derived growth factor (PDGF), promoting pulmonary fibrosis." (PMID 38609879, 2024). "Ample evidence supports that SiO2 activates inflammatory cytokines such as IL-1β, IL-6, TGF-β, TNF-α, growth factors, and CCL and promotes pulmonary fibrosis, suggesting that increased inflammatory cytokine levels may be used as typical biomarkers for the clinical diagnosis of silicosis." (PMID 38515835, 2024). "In addition, by inhibiting the activation of NF-κB in macrophages and lymphocytes, the expression levels of nitric oxide and tumor necrosis factor-α (TNF-α), interleukin (IL-1β), IL-6, transforming growth factor-β (TGF-β) and TNF in pulmonary fibrosis are reduced to prevent oxidative damage." (PMID 37089962, 2023). "In this study, the administration of hESC-MSC-IMRCs or hESC-MSC-IMRC-CM exhibited an ability to suppress TNF-α, IL-1β, and IL-6 release in lung tissues of BLM-challenged mice, suggesting that hESC-MSC-IMRCs or hESC-MSC-IMRC-CM could mitigate pulmonary fibrosis by relieving inflammatory responses." (PMID 36830999, 2023).